EPCAM (epithelial cell adhesion molecule)
Diseases named in the same sentence as EPCAM in open-access papers (continued):
Sharing a sentence is not in itself a finding about the gene and the disease.
cancer (continued). "In addition, the proteins (EpCAM and Integrin αv) which play vital roles in cancer homologous targeting were observed on U87MG cancer cell membrane (CM)." (PMID 37507371, 2023). "However, the reduced expression has been reported for EpCAM and cytokeratin for cancer cells undergoing epithelial-mesenchymal transition (EMT) during metastasis." (PMID 37303738, 2023). "Additionally, CSCs display specific surface antigens and markers, such as CD44 and CD133 in various cancers, as well as EpCAM in epithelial cancers." (PMID 37784157, 2023). "We established that 100–150 μM CoCl2 could be used to stimulate HIF-1α and growth factor receptors such as HER2 and the adhesion molecule EpCAM in order to grow and maintain CTCs isolated from the blood of cancer patients." (PMID 36879003, 2023). "In addition, we found that only approximately 50% of CTCs expressing the cancer-specific tissue of origin markers co-expressed EpCAM as assayed by IMC." (PMID 37568766, 2023). "In contrast, primary tissue-derived human CD44+ EpCAM+ ALDH1high ERα− cancer stem cells showed an abrogation by mTOR inhibitors during combination treatment with tamoxifen, which failed to prevent sphere formation alone until an mTOR inhibitor was introduced alongside it." (PMID 37904250, 2023). "However, since most cancers are of epithelial origin, there is a ‘universal’ epithelial molecular marker, EpCAM, which can be used for CTC detection." (PMID 36774504, 2023). "Moderate EpCAM expression in cancer cell lines varies from 400–600 MFI." (PMID 37192201, 2023). "Therefore, we stained for EpCAM, CD326, identifiable by its high expression on rapidly proliferating carcinoma of epithelial origin." (PMID 37275854, 2023). "Similarly, in our study, we observed different expression patterns of EpCAM among the studied carcinomas." (PMID 37627911, 2023). "With carcinoma-derived EpCAM being heavily glycosylated, this may result in a molecule with improved stability, cell surface presence, and enhanced signaling capacity." (PMID 37834237, 2023). "As EpCAM expression was shown to be highly specific in carcinomas, especially HNSCC, we used the epithelial marker EpCAM to characterize the largely unknown cell population in patient samples #1, #2, #3 and #13." (PMID 37370779, 2023). "Numerous promising EpCAM antibodies for cancer treatment have been reported in preclinical trials." (PMID 36369033, 2022). "In addition, several studies have shown co-overexpression of EpCAM and c-Met pathways and their significant interaction in developing resistance to currently targeted therapies in cancer tissues." (PMID 35986321, 2022). "In recent decades, extensive efforts have been made to decipher the role of EpCAM in cancers." (PMID 36369033, 2022). "Therefore, the EpCAM/VG-based electrochemical biosensor specifically binds the MCF-7, HT-29 and SW-403 cancer cells immobilized on the VG electrodes via EpCAM presence in the cell membrane." (PMID 36296024, 2022). "These Apt-PEG-Au-NPs@5-FU nanocarriers have several advantages as a therapeutic option in cancer therapy, including 1) high drug loading capacity, 2) enhanced drug release rate at acidic pH, and 3) ability of targeting HT-29 tumors by EpCAM Apt-mediated mechanisms." (PMID 36686226, 2022). "However, the expression levels of cancer stemness markers (EpCAM, Nanog and ALDH1A1) were much suppressed in MDA-MB-231 mammospheres (Day 14) in response to Oligo-Fucoidan or the combined treatment than olaparib alone." (PMID 36109724, 2022). "Since EpCAM is a widely expressed antigen by various cancer cells, this platform could be generalized for different types of CTCs capture and detailed analysis." (PMID 36140116, 2022).
cancer (continued). "The densely packed biotin could bind with streptavidin‐tagged anti‐EpCAM antibody, leading to a bioactive surface that enabled the recognition of EpCAM‐positive cancer cells." (PMID 37324582, 2022). "During epithelial-mesenchymal transformation, cancer cells might lose or lack their EpCAM expression." (PMID 36293034, 2022). "Physiologically, EpCAM is ubiquitously expressed on epithelial cells in organs including lung, colon, bladder, and breast, whereas in pathological conditions, EpCAM is specifically expressed in cancers originated from epithelial cells." (PMID 36077658, 2022). "Given the expression of CD47 and PD-L1 during tumorigenesis, designed EpCAM-targeted cationic liposomes containing si-CD47 and si-PD-L1 could target EpCAM-rich cancer cells to downregulate both CD47 and PD-L1 proteins." (PMID 36369033, 2022). "The tissue immunofluorescence staining at the junction of cancer and normal tissues of two representative NSCLC patients (Patient-7#/-13#) showed that ADCK2 expression (green fluorescence) in cancer cells was higher than it in epithelial cells (“Epi”, EpCAM labeling, in red fluorescence)." (PMID 36439873, 2022). "We identified the WT1 expression of the EpCAM+ cancer cells observed in MPE samples." (PMID 36293034, 2022). "Elevated expression of EpCAM in many cancers makes it an important therapeutic target." (PMID 36428553, 2022). "Moreover, the EpCAM-expressing cancer cells also showed positive staining for pERK, a KRAS downstream effector in PDAC 14,17." (PMID 35450328, 2022). "To determine how these optimized folate-derivatized beads might compare with standard anti-EpCAM-based beads, we suspended 100 KB cancer cells in 1 mL of cell culture medium and quantitated the efficiency of cancer cell retrieval using both types of beads." (PMID 35595733, 2022). "A precise extraction of ultra-thin fluid layers of CCM-CTCD during a rotational state permits high recovery rates and purity (recovery rates exceeding 90% and depletion rate of 99.9%) of a wide range of CTC subtypes including EpCAM(+), EpCAM(-), small and large cancer cells along with CTC clusters." (PMID 35664056, 2022). "The biological function of the glycoprotein EPCAM, a transmembrane glycoprotein mediating Ca -independent homotypic cell–cell adhesion, has been explored in cancer studies and it is known to participate in cell signaling, but little is known about its role in cattle." (PMID 35562812, 2022). "EpCAM is overexpressed in various cancers and the corresponding metastatic lesions." (PMID 35361871, 2022). "Downregulation of cancer stem cell markers octamer-binding transcription factor 4 (oct4), Notch1 (Neurogenic locus notch homolog protein 1), epithelial cellular adhesion molecule (EpCAM), and CD44 was observed in the stem cells embedded in mammosphere culture." (PMID 36362950, 2022). "Because PD-L1-negative EpCAM+ cancer cells, low PD-1 expressed CD8+T cells, and remarkably increased CD14+CD68+CD163+TIM-3+ macrophages were observed in MPE with disease progression, TIM-3 blockade therapy might be applicable to treatment." (PMID 36293034, 2022). "Another upregulated gene, EPCAM, has also been identified as a marker for cancer stem cells." (PMID 35631431, 2022). "EpCAM antibody–drug conjugates (ADCs) are also generated for EpCAM+ cancer therapies." (PMID 36369033, 2022). "These reasons support the use of EpCAM as a target receptor for cancer drug delivery systems." (PMID 35152538, 2022). "Cancer cells highly expressing EPCAM were harbored in ascites samples obtained at diagnosis." (PMID 36553542, 2022). "Other cancer studies also link EpCAM to the formation of new blood vessels." (PMID 35406725, 2022). "A homogeneous expression of SMAD4P130L might be a driver gene observed in EpCAM+ cancer cells in MPE." (PMID 36293034, 2022).
cancer (continued). "The results showed that the HIV peptides with the highest homology to TAAs identified in breast (CCR9), colon (EPCAM, GLOD5, CEACAM8) as well as prostate (NDUFS2) cancer and linked to most frequent HLA alleles (01:01; 02:01 and 24:02), are highly conserved across HIV isolates." (PMID 36243758, 2022). "EpCAM may be useful as an early marker for the maintenance of the undifferentiated state of hESCs and it can be considered as an important marker in cancer and EOC." (PMID 35563509, 2022). "Enhanced effectiveness by bispecific antibody targeting VEGFR2/EpCAM and its modulation of angiogenesis by decreasing IL-8 and IL-6 implied that EpCAM may be a promising target in preventing angiogenesis in cancer progression." (PMID 36369033, 2022). "EpCAM exerts its functions by mediating Wnt/β-catenin signaling in multiple cancers." (PMID 36369033, 2022). "Indeed, the strongest induction of EpCAM expression was observed by combination treatment in comparison with individual inhibitor in both human and murine highly metastatic cancer cells." (PMID 36077658, 2022). "However, currently CTCs are being trapped using antibodies against specific cancer types, with anti EpCAM as the most common antibody, directed mainly against solid tumors." (PMID 36361679, 2022). "Several studies have suggested EpCAM as a potential target for antibody therapy against cancers." (PMID 35628495, 2022). "EpCAM is one of the first cancer stem cell antigens to be reported." (PMID 36458008, 2022). "Moreover, PTEN reduction has been associated with increased expression of cancer stem cell markers [such as CD133, epithelial cell adhesion molecule (EpCAM), and CK19], HCC prognosis, and HCC recurrence." (PMID 36380016, 2022). "In fact, EpCAM has already found its place in CAR T cells for cancer treatment." (PMID 36369033, 2022). "As an adhesive molecule, the expression of EpCAM was speculated to be downregulated to increase the mobility of cancer cells." (PMID 36369033, 2022). "EPCAM has been recognized as an important therapeutic target for cancer." (PMID 36542699, 2022). "The BiTE of EnAd-SA-EpCAM binds to epithelial cell adhesion molecule (EpCAM) in cancer cells." (PMID 35756634, 2022). "Similarly, the same report demonstrated that for urothelial cell carcinoma, EpCAM and urokinase plasminogen activator receptor are complementary targets in cancer diagnosis." (PMID 36369033, 2022). "Whether genetic modification is involved in EpCAM downregulation in metastatic lung tumors and how EpCAM repression affects cancer metastasis are to be addressed in our further studies." (PMID 36077658, 2022). "EPCAM has high expressions in numerous human cancers, which originate from epithelial." (PMID 35150083, 2022). "BCG-infected cancer cells downregulate HLA class I and EpCAM membrane expression." (PMID 35503263, 2022). "It is worthwhile to develop cancer-specific anti-EpCAM mAbs using the CasMab method." (PMID 35735360, 2022). "YKL-40 gene expression was primarily increased in the fibroblast (gene annotation: COL1A, BGN, DCN), myeloid (gene annotation: CD68, LYZ, AIF1), cancer (gene annotation: EPCAM, KRT7, KRT18), and B-cell (gene annotation: CD79A, CD79B) populations in cancer tissue compared to healthy tissue." (PMID 35631632, 2022). "To note, CellSearch is limited to EpCAM-positive cells, and several studies showed how downregulation of EpCAM and epithelial-mesenchymal transition occur often in cancer and might reduce detection rate." (PMID 36081561, 2022). "There are several potential mechanisms of CD45+EpCAM+ cell formation in cancer tissue." (PMID 35711455, 2022).
cancer (continued). "However, the EpCAM protein is an epithelial marker normally found in most carcinomas, but is weakly expressed in HNSCC tumors." (PMID 35330447, 2022). "Therefore, SFN* peptide-based targeting paves the way for EpCAM-targeted cancer therapy as well as diagnosis." (PMID 34575511, 2021). "For cancer-related antigens on the lipid bilayer of exosomes, many different proteins can be utilized as biomarkers, depending on the host cancer cells, including HER2, CEA, EpCAM, IGFR, PSMA, etc., which are used as diagnostic and therapeutic markers." (PMID 33803846, 2021). "Together, our findings suggest that soluble/secreted EpCAM can suppress extracellular CTSL protease activity via its TY-1 domain, while cancer-associated EpCAM mutants that are not expressed on the cell surface do not retain this function." (PMID 33980181, 2021). "Cancer cells with an EMT phenotype display reduced EpCAM expression." (PMID 33550205, 2021). "For example, ADT levels of EPCAM on cancer/epithelial cells (c0, c4, c8, c14 and c15), CD31 (PECAM1) and CD34 on endothelial cells (c7 and c9), CD146 (MCAM) on perivascular cells (c11), CD90 (THY1) and CD34 on CAFs (c13) and CD45 (PTPRC) on immune cells (c3, c5 and c12)." (PMID 33971952, 2021). "Also, they used this system for the capture and release of epithelial cell adhesion molecule (EpCAM) expressing cancer cells." (PMID 34832761, 2021). "Moreover, EpCAM can be detected in the bodily fluid of cancer patients, suggesting that EpCAM is a biomarker for a variety of cancers." (PMID 34439276, 2021). "Epithelial cell adhesion molecule (EpCAM) is overexpressed in various cancer types including BC38." (PMID 33953198, 2021). "The biomarkers on the surface of the cancer cell membrane, such as T antigen-Galectin-3 and EpCAM, make cancer cells have homologous targeting and immunogenicity, which could overcome the environment of immune clearance and nonspecific attachment in vivo." (PMID 34596000, 2021). "EpCAM has been shown to promote invasion in other cell types and cancers." (PMID 34209658, 2021). "Catumaxomab kills EpCAM-positive cancer cells in malignant ascites and epithelial carcinomas." (PMID 34065315, 2021). "In addition, we observed significant downregulation of genes that mediate cell adhesion and EMT, including RHOB, shown to be required for neural crest delamination in the trunk, and EPCAM, which has been shown to participate in cancer cell EMT." (PMID 33613313, 2021). "The heterogeneity of EpCAM overexpression in tumors has been documented for many cancer types." (PMID 34439094, 2021). "First, we used the SingleR package and the known markers of cancer and alveolar cells to identify a cancer cluster and alveolar cluster; EPCAM and SOX4 were used to mark the cancer cluster; SFTPC and SFTPA1 to mark the alveolar cluster; CAPS and TPPP3 to mark epithelial cells." (PMID 33783985, 2021). "In addition, a novel aptamer-PEI-siRNA nanoparticle was utilized for targeting the putative cancer stem cell marker EpCAM, leading to inhibition of the cancer cell proliferation." (PMID 34959397, 2021). "Since it is upregulated in some cancers and contributes to metastatic behaviors such as proliferation and migration, it may likewise help to confer homotypic recognition between biomimetic carriers and cancers with high EpCAM expression levels." (PMID 34070233, 2021). "We also tested the ability of cancer cell lines transduced with EpCAM to inhibit CTSL." (PMID 33980181, 2021).
cancer (continued). "Epithelial cell adhesion molecule (EpCAM) is a transmembrane glycoprotein that plays an important role in Ca2+-independent hemophilic cell-to-cell adhesion, cell signaling, migration, proliferation, and differentiation of cancer cells." (PMID 34900726, 2021). "In cancer, this may be controlled somewhat paradoxically by EpCAM’s selective and relatively weak aggregative abilities in conjunction with its negative effects on cadherin and tight junction formation." (PMID 34209658, 2021). "There might be a window or stage that requires different functions of EpCAM during the process of EMT in cancer cells to further participate in the metastasis process." (PMID 33691694, 2021). "When binding with EpCAM, claudin-7 promotes cancer progression, while when binding with integrin β1, claudin-7 maintains cell-matrix adhesion and suppresses the growth and movement of cancer cells." (PMID 34354941, 2021). "Oportuzumab Monatox is an immunotoxin, binding specifically to the epithelial cell adhesion molecule (EpCAM), which is a transmembrane glycoprotein, frequently overexpressed in different cancers, inter alia malignancies of the colon, intestine, breast, lung, and prostate." (PMID 34123841, 2021). "EpCAM is also reported to be expressed in normal cells, and thus we investigated whether EpCAM CAR T could show selective cytotoxicity to cancer cells compared with normal cells." (PMID 34790117, 2021). "However, genes associated with cell differentiation (EPCAM, CK8, CK18, and FOXA2), EMT (SNAI1, FOSL1, and ID1), and cancer stem cells (CD44, CD133, ETV1, MALAT1, NEAT1, and NESTIN) displayed a more varied response compared to 2D cells." (PMID 33356003, 2021). "The epithelial cell adhesion molecule EpCAM is expressed in many cancer tissues including TCC." (PMID 33837852, 2021). "With the exception of MMP-9 mRNA in OVCAR4 cells, CIS and PTX both significantly increased the expression of MMP-2, -9 and -14 mRNAs and concurrently increased the expression of three CSC markers (OCT4A, EpCAM, CD133), associated with chemoresistance in the cancer cell lines." (PMID 35047406, 2021). "Another important limitation in this setting is represented by the fact that the levels of EpCAM in cancer stem cells could be lower than in the bulk tumor mass, and therefore CTCs would not display cancer stem cells." (PMID 34208918, 2021). "Consequently, EpCAM-positive cancer cells are highly efficiently killed by catumaxomab, which induces a concerted attack of T cells and accessory immune cells like monocytes, dendritic cells and NK-cells and thereby even elicits a vaccination effect." (PMID 33837852, 2021). "On the one hand, EpCAM expression is decreased when cancer cells undergo EMT." (PMID 33691694, 2021). "EpCAM(+)/CD44(+) cells grow exponentially in vitro as cancer spheres with SFM culture." (PMID 34350176, 2021). "EpCAM also exhibited inversely correlated with CD8+ T cells infiltration in cancers." (PMID 34790117, 2021). "It has been reported that high positivity of CTCs indicates poor prognosis in patients with HCC and is associated with poor clinicopathological parameters, but the characteristically low EpCAM expression in this cancer has made standard CTC measurements difficult." (PMID 33675149, 2021). "EpCAM is overexpressed in many epithelial cancers, and plays a complex role in cancer biology, stimulating or inhibiting diverse cancer signaling pathways depending on the cancer type." (PMID 33980181, 2021). "This system efficiently identified characteristic CD9, CD44 and epithelial cell adhesion molecule (EpCAM) surface proteins, demonstrating that it could be used for cancer diagnosis and cell phenotype characterization." (PMID 34440265, 2021). "It is an anti-EpCAM coated wire which is inserted into the vein of patients via an intravenous cannula for 30 min to allow for the direct sampling of CTCs from the peripheral blood of cancer patients." (PMID 33652649, 2021).